HMGB1 (high mobility group box 1)
Diseases named in the same sentence as HMGB1 in open-access papers (continued):
Sharing a sentence is not in itself a finding about the gene and the disease.
breast carcinoma (continued). "Furthermore, HMGB1 enhanced breast cancer cell migration, invasion, and EMT, contributing to tumor growth in an in vivo mouse model that were mitigated by the HMGB1-targeted approach." (PMID 40389855, 2025). "Indeed, radiation‐induced HMGB1 released from cancer cells has shown to activate the systemic immune response in several tumor types, including the 4T1 mammary tumor." (PMID 40400098, 2025). "Additionally, TAMs/CXCL1 silence improved paclitaxel chemosensitivity by suppressing autophagy in breast cancer mice xenografts, and clinical studies further linked CXCL1 to IGF1R/HMGB1 signaling, as well as shorter free survival of recurrence." (PMID 39394189, 2024). "HMGB1 plays a role in the development of oral, lung, colon, and breast cancer." (PMID 37897664, 2024). "The knockdown of HMGB1-RAGE-PI3K/AKT pathway could attenuate breast cancer cell aggressive phenotypes and overcome resistance to anti-tumor treatment." (PMID 39830522, 2024). "Recent studies reported an interplay between the receptor for advanced glycation end products (RAGE) and its ligands, S100 protein group, advanced glycation end products (AGEs) and high-mobility group box 1 protein (HMGB1) and breast cancer growth and metastasis." (PMID 39830522, 2024). "Moreover, univariate COX analysis showed that the factors including tumor stage, N stage, CD163 expression, CXCL1 expression, HMGB1 expression, and IGF1R expression were significantly associated with breast cancer prognosis." (PMID 39394189, 2024). "Previous studies suggested that CXCL1 could induce autophagy-mediated chemoresistance in breast cancer cells by regulating HMGB1." (PMID 39394189, 2024). "Similarly, an additional study revealed increased HMGB1 expression in breast cancer cells after coculture with CAFs, wherein the heightened HMGB1 levels increased resistance to doxorubicin in cancer cells through the potentiation of autophagy." (PMID 38649701, 2024). "Neural stem and progenitor markers such as MSI1, DCX, NFL, HMGB1 were all significantly decreased after co-culture with breast cancer cells, suggesting that interaction with breast cancer cells leads to initiation of neural differentiation and maturation of NPCs." (PMID 39232464, 2024). "In addition, the interaction between HMGB1-RAGE promotes breast cancer cell invasion through PI3K/AKT signaling pathway." (PMID 39830522, 2024). "Research has shown that fibroblasts in breast cancer activate HMGB1 release into the tumor microenvironment, where it interacts with RAGE and promotes invasion of breast cancer cells and the expression of programmed death ligand 1 (PD-L1) through the PI3K/AKT signaling pathway." (PMID 38529373, 2024). "Notably, breast cancer patients exhibiting high HMGB1 expression are more prone to develop cancer metastasis, especially in triple-negative breast cancer." (PMID 38203626, 2023). "GPR30 is highly expressed in breast-cancer-associated fibroblasts, and GPR30-induced gene activation results in an enrichment of high mobility group box 1 (HMGB1), which induces tamoxifen resistance through the MEK–ERK signaling pathway while increasing autophagic activities." (PMID 37190065, 2023). "Furthermore, PKHB1-induced cell death exhibits key molecular hallmarks of ICD, including the exposure of calreticulin, HSP70, HSP90, and the release of ATP and HMGB1 in various leukemic and breast cancer cell lines." (PMID 38077402, 2023). "Recently, a role for HMGB1 blockage in breast cancer and immunotherapy has been uncovered." (PMID 37190065, 2023). "GPR30 triggered PI3K/mTOR axis to elevate the extracellular secretion of HMGB1 (High mobility group box 1) in CAFs which led to the activation of the MEK/ERK axis in neighboring ERα-positive breast cancer cells and thereby induction of autophagy to accelerate tamoxifen resistance." (PMID 37900137, 2023).
breast carcinoma (continued). "Breast cancer cells may be inhibited from autophagy, proliferation, and migration by HMGB1; in addition, several research studies have discovered that miR-107 controls PTX sensitivity via Wnt/-catenin signaling pathway, which targets TPD52." (PMID 36816358, 2023). "The attenuating HMGB1-RAGE-PI3K/AKT pathway may help to attenuate breast cancer cell aggressive phenotypes." (PMID 35610613, 2022). "However, there is a paucity of reports on how RNA sponges, or even competing endogenous RNA (ceRNA) regulatory networks, impact HMGB1-mediated breast cancer progression." (PMID 35637945, 2022). "This study has shown that cancer-associated fibroblast substances can activate HMGB1 expression and secretion by cancer cells, which can then be released into the tumor microenvironment and the HMGB1-RAGE interaction promotes breast cancer progression and drug resistance." (PMID 35610613, 2022). "The different patterns of HMGB1 induction determine its subcellular distribution, influence HMGB1-related biological processes such as autophagy, immunogenic cell death, and ultimately the efficacy of chemotherapy and radiotherapy for breast cancer." (PMID 35637945, 2022). "Cytoplasmic mRNA translocation and release of HMGB1 were previously ascribed to mesothelial cells within mesothelioma tissue, and the role of CAFs in releasing DAMPs has so far only been reported in the context of autophagy in breast cancer." (PMID 36293328, 2022). "From different perspectives, HMGB1 enforces different functions in breast cancer chemotherapy." (PMID 35637945, 2022). "The function of HMGB1 in the metastatic process of breast cancer has been more frequently reported." (PMID 35637945, 2022). "Therefore, blocking the geminin-HMGB1/RAGE signaling axis has also been attempted as a strategy to inhibit breast cancer cell proliferation and metastasis." (PMID 35637945, 2022). "Thus, it is likely that HMGB1-RAGE interaction promotes breast cancer cell invasion via PI3K/AKT signaling." (PMID 35610613, 2022). "Furthermore, HMGB1-mediated immune activity indicates the new potential about immunotherapy for breast cancer, liberating the possibilities for innovation of combination therapeutic strategies." (PMID 35637945, 2022). "HMGB1-mediated autophagy occupies an important part in breast cancer." (PMID 35637945, 2022). "There are more reports about HMGB1/TLR4 interactions in breast cancer progression." (PMID 35637945, 2022). "The macrophage migration inhibitory factor could induce breast cancer cell migration and metastasis via HMGB1/TLR4/NF-κB activation." (PMID 35610613, 2022). "HMGB1 is engaged in many stages of breast cancer progression." (PMID 35637945, 2022). "However, the dual anti-tumor and pro-tumor biological functions of HMGB1 make its precise role in breast cancer progression quite elusive." (PMID 35637945, 2022). "The clinical value of HMGB1 in breast cancer has been generally established." (PMID 35637945, 2022). "Due to the complexity of HMGB1 functions in breast cancer progression, new therapeutic strategies targeting HMGB1 are constantly being developed, such as the identification of potential ICD inducers and the combination therapies with immune checkpoint blockade 18-20." (PMID 35637945, 2022). "It remains to be determined whether such a mechanism is indeed happening in breast cancer cells by the action of the HMGB1-RAGE interaction or if this could be a target for therapeutic intervention." (PMID 35610613, 2022). "Stromal fibroblast cells in breast cancer may also play a similar role in chemoresistance through upregulation of HMGB1 in cancer cells during chemotherapy-mediated cell death." (PMID 35340325, 2022). "Hence, from the findings herein, it can be concluded that the pathways in breast cancer by which extracellular HMGB1 promotes disease aggressiveness are mainly through invasion via RAGE." (PMID 35610613, 2022).
breast carcinoma (continued). "Furthermore, the findings showed that compared with the normal control group, the total protein and phosphorylation level of HMGB1 at the S35 locus in the primary tumour was significantly lower for breast cancer, LUAD and UCEC (all p < 0.01)." (PMID 35765707, 2022). "The inhibitions of HMGB1 and its related signaling pathways report previously may be proposed to facilitate the efficacy of T cell therapy in breast cancer patients." (PMID 35610613, 2022). "Moreover, hematological and neurological expressed 1-like (HN1L) protein can interact with HSPA9 to upregulate HMGB1 expression and play a key role in promoting breast cancer cell invasion and metastasis." (PMID 35637945, 2022). "HMGB1 overexpression in breast cancer tissue indicates metastasis, TNM stage, and differentiation." (PMID 36151122, 2022). "This literature review confirmed the present study where HMGB1 could regulate breast cancer aggressiveness through RAGE-PI3K/AKT signaling pathway-controlled PD-L1 expression." (PMID 35610613, 2022). "In this study, we delineated an interaction by which CAFs might contribute to the TAM-acquired resistance of breast cancer cells via the paracrine action of HMGB1." (PMID 34182538, 2021). "HMGB1 has been shown, using an in vivo model, to enhance vessel formation in breast cancer cells." (PMID 33711197, 2021). "HMGB1 is expressed highly in patients with TN breast cancer and may be involved in lung metastasis in combination with CD62Ldim neutrophils." (PMID 34638242, 2021). "Considering that HSPA9 is involved in cell senescence and HMGB1 is one of the markers of cell senescence, we hypothesize that HNIL may interact with HSPA9 and participate in breast cancer cell invasion and metastasis mediated by HMGB1." (PMID 33191617, 2021). "Similarly, miR-107 expression is reduced in breast cancer, and miR-107 inhibits breast cancer cell proliferation and migration via targeting and suppressing HMGB1." (PMID 33926489, 2021). "Thus, HMGB1 is involved in drug resistance via the positive regulation of autophagy in breast cancer cells, as in other types of cancer cell." (PMID 34638242, 2021). "Similarly, HMGB1 levels in breast cancer (n=232) positively correlate with favorable prognosis, while in pancreatic cancer (n=78), high HMGB1 is unfavorable." (PMID 33821233, 2021). "ER stress induces HMGB1 secretion in TN breast cancer cell lines, and the cytoplasmic expression of HMGB1 correlates positively with the abundance of TILs in TN breast cancer, suggesting that HMGB1 secretion mediates subsequent tumor-specific immune activation by CTLs." (PMID 34638242, 2021). "Similarly, the suppression of mediator complex subunit 19 down-regulated autophagy by inhibiting HMGB1 signaling and enhanced doxorubicin chemosensitivity in human breast cancer cells." (PMID 34638242, 2021). "Previous studies have suggested that extracellular HMGB1 could enhance and maintain the stemness of CSCs in breast cancer, colorectal cancer and pancreatic cancer." (PMID 33614649, 2021). "A study indicated that the nuclear expression of HMGB1 in breast cancer cells negatively correlates with Tregs and TAMs, and could predict the recurrence risk of residual tumor." (PMID 34283088, 2021). "miR-142-3p by targeting HMGB1 could enhance chemosensitivity of breast cancer cells and inhibits autophagy." (PMID 34804971, 2021). "In addition, patients with endocrine therapy (ET)-refractory HR-positive breast cancer showed greater HMGB1 expression correlated with worse postoperative progression-free survival (PFS)." (PMID 34638242, 2021). "In breast cancers, activated cancer-associated fibroblasts (CAFs) regulate the BCSCs and support stem-cell-like characteristics through factors such as monocyte chemotactic protein-1 (CCL2), IL6, IL8, and high-mobility group box 1 (HMGB1)." (PMID 32883003, 2020).
breast carcinoma (continued). "We believe that the expression level of tumor tissue or serum HMGB1 combined with the PB CD62Ldim neutrophil percentage may be a prospective strategy to predict the possibility of tumor metastasis in breast cancer patients." (PMID 32943604, 2020). "To elucidate the role of HMGB1 in breast cancer, we used a 4T1 orthotopic mouse model of TNBC." (PMID 32943604, 2020). "Furthermore, serum HMGB1 levels were positively correlated with CD62Ldim neutrophils in 86 breast cancer patients." (PMID 32943604, 2020). "Moreover, breast cancer patients with lung metastasis were shown to express higher levels of HMGB1 than 10-year metastasis-free patients." (PMID 32943604, 2020). "Furthermore, we selected 80 pathology sections of primary breast cancer and divided them into 5 groups based on the HMGB1 expression intensity in tumor cells and established scoring criteria." (PMID 32943604, 2020). "Serum levels of HMGB1 and the frequency of MDSCs are correlated and increased in breast cancer patients, MDSCs cultured under starvation conditions and in the presence of ethyl pyruvate do not upregulate autophagic markers and have their viability drastically reduced." (PMID 31379812, 2019). "Recently, Mir-107 could inhibit cell autophagy, proliferation, and migration of breast cancer cells by targeting HMGB1 has been reported." (PMID 30704538, 2019). "An immediate increase in HMGB1 levels correlates with improved outcomes in early breast cancer patients receiving neoadjuvant chemotherapy, and may be a valuable complementary biomarker for early prognosis." (PMID 30744691, 2019). "However, no study has focused on the association of miR-129-5p dysregulation and the sensitivity of breast cancer cells to Taxol by targeting HMGB1." (PMID 31664305, 2019). "Moreover, autophagic CAFs can promote stemness of luminal breast cancer cells by releasing HMGB1 (high-mobility group box 1)." (PMID 31555586, 2019). "Using miR-129-5p/HMGB1/autophagy-based therapeutic strategies may be a potential treatment for overcoming Taxol resistance in breast cancer." (PMID 31664305, 2019). "DOC treatment drives HMGB1 release, acting as a potential antitumor immune response inducer in metastatic breast cancer cells, but the response of NSCLC patients to neoadjuvant chemotherapy (NCT) was unknown." (PMID 30744691, 2019). "A recent paper demonstrated that extracellular HMGB1 could induce breast cancer metastasis by binding to TLR4 in a macrophage inhibitory factor (MIF)-dependent manner." (PMID 31779212, 2019). "It was reported that HMGB1 regulated radiosensitivity of breast cancer and bladder cancer." (PMID 29567990, 2018). "HMGB1 is capable of promoting both chemoresistance and radioresistance in breast cancer cells." (PMID 28376901, 2017). "HMGB1 knockdown could promote the radiosensitivity of breast cancer cells through breaking telomere homeostasis and inhibiting the repair of DNA damage." (PMID 28376901, 2017). "Taken together, these results suggest that autophagy blockade or HMGB1 loss in breast cancer cells have a negative impact on the anticancer immune surveillance." (PMID 27917371, 2016). "Studies in mouse models show that cyclophosphamide is less effective against HMGB1-negative tumors, and that human breast cancer patients carrying a TLR4 loss-of-function allele have a poor prognosis." (PMID 25755254, 2015). "Interestingly, the prototypical marker of MDSCs, ARG1, was amongst the shared genes, whereas HMGB1 is specific for monocytes derived from breast cancer patients." (PMID 25992611, 2015). "HMGB1 is overexpressed in many types of cancer including breast cancer." (PMID 25512109, 2014). "In addition to this intrinsic expression, breast cancer cells can be stimulated by factors released from activated fibroblasts to increase their expression of HMGB1." (PMID 25512109, 2014). "The role of such fibroblasts in HMGB1 production in breast cancer is unclear." (PMID 25512109, 2014).
breast carcinoma (continued). "Doxorubicin is commonly used in breast cancer treatment and our results using real time PCR showed that this drug could induce intracellular HMGB1 expression in MDA-MB-231 cells in a concentration-dependent manner." (PMID 25512109, 2014). "In the present study, MDA-MB-231 breast cancer cells were induced by BCF-CMs (or by Dox) to express high levels of HMGB1.When cell death was induced, HMGB1 could be subsequently released." (PMID 25512109, 2014). "The findings reported here highlight the potential of cancer-stromal fibroblast interactions to drive chemoresistance in breast cancer in part as a result of fibroblast-induced HMGB1 production and release into the tumor microenvironment with paracrine effects on neighboring cancer cells." (PMID 25512109, 2014). "This pilot study investigates the immunomodulatory effects of cryoablation in early breast cancer (BC) patients by analyzing blood and surgical samples, with a focus on T-cell subsets, regulatory T cells (Tregs), serum cytokines, and high-mobility group box 1 (HMGB1) levels." (PMID 41428121, 2025). "Furthermore, rs243842 and rs243867 of the MMP2 gene showed statistically significant associations with a poor breast cancer prognosis regarding DFS, while among OS patients rs243842 in the MMP2 gene and rs4145277 in the HMGB1 gene were significantly associated with poor prognosis." (PMID 39830522, 2024). "The interference of Hsp60 and HMGB1 could influence the growth of 4T1 breast cancer cells in an autocrine manner, while the inhibition of Hsp60 triggered cyclophilin D-dependent mitochondrial permeability transition and caspase-dependent cell death in MCF-7 breast cancer cells." (PMID 38255948, 2024). "In addition, CXCL1/HMGB1 autophagic axis might be triggered following chemotherapy in breast cancer." (PMID 39394189, 2024). "Thus, targeting RAGE and HMGB1-mediated signaling pathways could be an innovative approach for therapeutic intervention and prevention strategies in breast cancer management." (PMID 39830522, 2024). "In addition, HMGB1 is engaged in estradiol (E2)-mediated autophagosome formation in breast cancer." (PMID 35637945, 2022). "However, there are conflicting reports on the resistance of HMGB1 to breast cancer radiotherapy." (PMID 35637945, 2022). "This review focuses on the function of HMGB1 in breast cancer based on its biological characteristics and summarizes the valuable preclinical and clinical evidence in breast cancer treatment, with the aim of providing insights for the innovation of therapeutic strategies targeting HMGB1." (PMID 35637945, 2022). "The RAGE-knocked down (KD) breast cancer and inhibitors against PI3K and AKT were applied to investigate that RAGE-PI3K/AKT signaling pathway activated by HMGB1 could regulate aggressive breast cancer cell properties and PD-L1 expression leading to acquired resistance to breast cancer treatment." (PMID 35610613, 2022). "They found that the levels of HMGB1 in breast tissues and serum were significantly higher in breast cancer patients than in patients with benign breast disease or the normal population, suggesting that serum HMGB1 may be a useful serological biomarker for the diagnosis of breast cancer." (PMID 35637945, 2022). "According to these findings, HMGB1 plays a pivotal role in CAFs-mediated breast cancer progression and chemoresistance, and targeting HMGB1 may be an effective strategy to diminish chemoresistance in breast cancer." (PMID 35637945, 2022). "Tumorigenesis and breast cancer progression induced by HMGB1 as a ligand may be mediated via the TLR4/myeloid differentiation factor 88 and RAGE signaling pathways for tumor invasion and metastasis, CSC renewal, epithelial–mesenchymal transition (EMT), drug resistance, and cancer recurrence." (PMID 34638242, 2021).